GLI2 (GLI family zinc finger 2)
Diseases named in the same sentence as GLI2 in open-access papers (continued):
Sharing a sentence is not in itself a finding about the gene and the disease.
panhypopituitarism (1 paper, 2020). Insufficient production of all the anterior pituitary hormones. "In light of this genetic analysis of either asymptomatic or symptomatic relatives for GLI2 gene mutations and evaluation of carriers for panhypopituitarism is warranted." (PMID 31782289, 2020). "GLI2 mutations leading to a truncated protein usually cause panhypopituitarism, polydactyly and midfacial hypoplasia, which were present in our index case." (PMID 31782289, 2020).
Pc (1 paper, 2017). "HSCs/myofibroblasts (>99%) expressed GLI2, with only 1.92% displaying Pc." (PMID 28187190, 2017).
pituitary deficiency (1 paper, 2016). "Although the defining medial forebrain deficiency of true HPE has been identified in several individuals with single-allele GLI2 mutations, most cases involve more subtle abnormalities, such as pituitary deficiency and/or facial dysmorphology." (PMID 27585885, 2016).
polycystic kidneys (1 paper, 2017). "In a postnatal deletion of Ttc21b, increased GLI2 activity led to polycystic kidneys." (PMID 29615573, 2017).
psychosis (1 paper, 2021). "The rare variant identified in GLI2 may also contribute to the psychosis phenotype." (PMID 33897758, 2021).
respiratory allergy (1 paper, 2018). "So regardless the complexity of GLI2-dependent transcription, in the sections below, we describe the plausible pathways via which GLI2 hypermethylation could increase the risk of respiratory allergies." (PMID 29682088, 2018). "It is important to notice that the function of GLI2 can be dependent of the type of tissue in which it is expressed, but GLI2 is important for lung development and altered expression might thus have an influence on the risk to develop respiratory allergies when GLI2 methylation status is altered." (PMID 29682088, 2018). "One DMR in the GLI2 promoter region showed a consistent statistically significant hypermethylation in individuals with respiratory allergy across the two birth cohorts and technologies." (PMID 29682088, 2018). "This study identified hypermethylation in a CpG shore of the GLI2 gene promoter, which discriminates school-age children with a respiratory allergy from healthy control children using saliva samples." (PMID 29682088, 2018). "In the current study, we identified a DMR in the GLI2 gene that distinguishes children with a respiratory allergy from healthy controls." (PMID 29682088, 2018). "We found hypermethylation in the GLI2 gene in saliva from school-age children with a respiratory allergy when compared to saliva from healthy control subjects." (PMID 29682088, 2018). "As such, it can be postulated that GLI2 hypermethylation is involved in the suppression of the cell cycle, with a possible negative effect on lung development and an increased chance of developing respiratory allergy." (PMID 29682088, 2018). "GLI2 is considered an interesting candidate DNA methylation marker for respiratory allergy." (PMID 29682088, 2018).
sarcopenia (1 paper, 2024). Progressive decline in muscle mass due to aging which results in decreased functional capacity of muscles. "Sarcopenia was nominally associated (p < .05) with 12 tRNAs, 3 tRFs, and 6 piRNAs, with target genes linked to cell proliferation and differentiation such as Notch Receptor 1 (NOTCH1), DISC1 scaffold protein (DISC1), and GLI family zinc finger‐2 (GLI2)." (PMID 38294260, 2024). "In our study there was a positive association between tRF‐5003c and sarcopenia status suggesting that increased tRF‐5003c expression may contribute to the reduced expression of NOTCH, DISC1, and GLI2 and impaired muscle function." (PMID 38294260, 2024).
scoliosis (1 paper, 2025). A congenital or acquired spinal deformity characterized by lateral curvature of the spine. "In the present study, severe scoliosis causes Gli2 knockout subjects to be relatively anteroposteriorly compressed compared to wildtype counterparts and to have a different angle between the head and torso." (PMID 40832189, 2025). "Gli2 knockout subjects differ in overall shape from wildtype subjects due to severe scoliosis and large displacements of internal organs." (PMID 40832189, 2025).
skin inflammation (1 paper, 2019). "Thus, conditional Gli2-mediated transcription in T cells impaired induction of AD and rescued skin pathology, showing that elevated T cell autonomous Hh pathway activation can, and is sufficient, to protect against skin inflammation in AD." (PMID 31264977, 2019).
steatosis (1 paper, 2016). Increased lipid within the cytoplasm of cells. "Ad (iii), to proof the assumption that reversal of the level of the Gli TFs (GLI1 and GLI3) is able to overcome steatosis we treated isolated hepatocytes from steatotic ob/ob mice with overexpression plasmids for GLI1, GLI2, GLI3 and a combination of GLI1 and GLI3." (PMID 27185526, 2016).
Tracheomalacia (1 paper, 2020). "Gli2−/−;Gli3+/− mouse embryos that have only one copy of Gli3 also exhibit tracheomalacia, whereas Gli2+/−;Gli3−/− embryos, which lack Gli3 but have a single copy of Gli2, do not." (PMID 33328171, 2020). "Similarly, Gli2−/−;Gli3+/− germline mouse mutants, with one copy of Gli3R but no Gli2A, displayed tracheomalacia, whereas Gli2+/−;Gli3−/− mice, which lack Gli3R, do not." (PMID 33328171, 2020).
Urinary incontinence (1 paper, 2016). Loss of the ability to control the urinary bladder leading to involuntary urination. "In addition, female Gli2+/–;Gli3Δ699/+ mice invariably displayed urinary incontinence (data not shown)." (PMID 27814383, 2016).
uveitis (1 paper, 2018). An inflammatory process affecting a part of or the entire uvea. "GLI2 (ENSP00000354586) was also regarded as a potential pathogenic gene of uveitis." (PMID 30349554, 2018). "For its specific contribution on uveitis, GLI2 regulates Notch-Gli2 axis and hedgehog signaling pathway; however, no direct reports confirmed its pathogenic role." (PMID 30349554, 2018).
tumor (266 papers, 2006 to 2026). "We examined the association of TGFβ3/GLI2/YAP1 with tumor infiltration of various immune and immunosuppressive cells." (PMID 40027190, 2025). "Longitudinal CNV profiles displayed evolution in both tumor and CSF samples, including the emergence of high-risk molecular features such as GLI2 amplification." (PMID 40579709, 2025). "Absence of these markers defines a low-risk group similar to WNT tumour patients, highlighting GLI2 and 14q loss as reliable prognostic indicators." (PMID 39568072, 2024). "SMO inhibition causes the transcription factors GLI1 and GLI2 to remain inactive, preventing tumour-mediating genes’ expression within the Hedgehog pathway." (PMID 37240278, 2023). "In invasive tumors, we have determined that the loss of Gli2 and Gli3 in fibroblasts decreases myeloid-derived suppressor cells (MDSCs) and increases natural killer (NK) cells, which in turn antagonize tumor growth." (PMID 35867772, 2022). "In contrast, combining Gli2 knockdown with DDP treatment caused a marked decrease in the tumor volume and mass." (PMID 35059317, 2021). "Taken together, SETDB2 interacts with ΔNp63α, methylates and stabilizes the ΔNp63α protein to upregulate the Hedgehog pathway-associated genes CXCR4, PTCH1 and GLI2, which promote stem cell maintenance, tumor initiation and growth." (PMID 32549764, 2020). "Most strikingly, 3 days after transgene induction mTOR/S6 signaling was activated strictly in GLI2A-expressing nascent tumor cells at the base of gastric glands, establishing a tight association between the Hh/Gli2 and mTOR pathways during tumor initiation." (PMID 26859571, 2016). "On the other hand, if tumors were initiated with a constitutively active form of Gli2, which would be downstream of Smoothened function, loss of cilia accelerated tumor growth." (PMID 24594320, 2014). "Type 3A exhibited the nuclear accumulation of GLI2, suggesting that the hedgehog pathway was activated like Type 1 and Type 2, probably by a tumor cell-specific somatic mutation." (PMID 23951062, 2013). "This high expression level of Gli2 was significantly associated with tumor differentiation, encapsulation, vascular invasion, early recurrence, and intra-hepatic metastasis (P < 0.05)." (PMID 23356443, 2013). "NK cell depletion reversed the tumor-suppressive effect of Gli2/Gli3 loss, restoring tumor growth." (PMID 39859231, 2025). "Mutations in OFD1 lead to cilia loss, resulting in slow-growing, GLI2-dependent resistant tumours." (PMID 39568072, 2024). "In addition, in the case of diagnostic difficulties, the identification of the GLI2 rearrangement allows to classify the neoplasm as SST." (PMID 38136408, 2023). "Notably, the depletion of NK cells in tumors co-injected with Gli2/Gli3 KO fibroblasts rescues tumor growth, suggesting that the loss of Gli2/Gli3 in fibroblasts restrains tumor growth through the recruitment of NK cells." (PMID 36674836, 2023). "Mechanisms of resistance could be associated with SMO mutations and amplification of GLI2, underlining the importance of this transcription factor for sustained tumor growth." (PMID 28418873, 2017). "While it was shown that fibronectin greatly affects the expression of tumor-produced factors associated with bone destruction (parathyroid hormone-related protein, PTHrP, and Gli2), poly-l-lysine, vitronectin and type I collagen were also analyzed as potential matrix proteins." (PMID 26306316, 2015). "Analyzing the association of Gli2 expression with pathologic characteristics in 68 patients with HCC identified a significant correlation of Gli2 expression with tumor differentiation, encapsulation, vascular invasion, early recurrence, and intra-hepatic metastasis." (PMID 23356443, 2013).
tumor (continued). "Through an analysis using both the TCGA database and our own collected samples, we observed elevated levels of GLI2 expression in GC tissues that were significantly associated with the patient’s differentiation degree, pathological grade, lymph node metastasis, and tumor size." (PMID 40133270, 2025). "Similarly, Gli2 could substitute Ci together with knockdown of hib to cause the tumor-like eye phenotype." (PMID 37554435, 2023). "In preclinical models, a contrasting approach—directly inhibiting the GLI transcription factors (e.g., GLI2 with GANT61)—has shown substantial anti-tumor activity." (PMID 41522355, 2026). "This indicates that combined Gli2/Gli3 deletion in fibroblasts suppresses tumor growth specifically through enhanced NK cell recruitment." (PMID 39859231, 2025). "Consistently, GANT61, a confirmed inhibitor of GLI, effectively suppresses the in vivo expression of GLI2 and markedly reduces tumor volume and weight." (PMID 40133270, 2025). "The two-group comparison—tumor/normal—showed, interestingly, a tumorous downregulation of the expression levels of GLI2 and GLI3." (PMID 40565349, 2025). "Gli2 and Gli3 are key mediators of Hedgehog signaling that regulate various cellular processes, including tumor–stroma interactions and immune modulation." (PMID 39859231, 2025). "Mechanistically, TM exerted anti-tumor effects via downregulating GLI2, and its downtream targets, thus inhibiting the sonic hedgehog (SHH) signaling pathway." (PMID 39881254, 2025). "GLI2, is a transcription factor that regulates the expression of genes that in turn regulate tumor growth." (PMID 40140215, 2025). "Recent studies have revealed that GLI2 influences the chemoresistance of GC cells by modulating tumor stem cell promotion." (PMID 40133270, 2025). "Glioma-associated oncogenes (GLIs) consist of three members: GLI1, GLI2, and GLI3, which are the downstream transcription factors involved in mediating the signaling pathway and leading to tumor progression." (PMID 40133270, 2025). "IHC detection of tumor tissue from BALB/c Nude mice further validated the in vivo regulation of DEC1 expression by GLI2." (PMID 40133270, 2025). "Expression of Gli2 in mouse epidermis is sufficient to induce BCC-like tumours; in human keratinocytes, it induces a number of genes involved in G1–S phase and G2–M phase progression and induces genomic instability by inhibiting apoptosis." (PMID 41373535, 2025). "Transcriptomic and functional analyses revealed that TM treatment led to the decrease of GLI2 and inhibition of the SHH signaling pathway, accounting for the underlying mechanism of its anti-tumor activity." (PMID 39881254, 2025). "First, we examined the expression of GLI2 in relation to the grade of CAF tumor infiltration, an indicator of levels of fibrosis, in The Cancer Genome Atlas samples (Pan-Cancer atlas, 2018)." (PMID 40449600, 2025). "Next, we analyzed the correlation between GLI2 and HOTTIP expression levels and found that, in all tumor patients, high GLI2 expression was associated with high HOTTIP expression." (PMID 40624028, 2025). "Analysis of the mechanism using RNA sequencing demonstrate higher levels of GLI2 targets, particularly tumor growth–promoting genes, including Ccnd1, N-Myc, and Bcl2, in KrasG12D mutant cells." (PMID 38896052, 2024). "This, taken together with a stronger signal of GLI2 in tumors compared to non-tumor tissues, suggests that the Hedgehog pathway is indeed activated in sinonasal adenocarcinoma." (PMID 38731849, 2024). "Chromothripsis can cause SHH pathway gene amplification, such as GLI2 and MYCN, which increases SHH target gene expression and drives tumor development." (PMID 38391759, 2024). "Consistent with the increased penetrance and severity, the levels of Gli1, Gli2, and Sufu expression were higher in Ptch1–/+;3nSD MB tumor tissues compared with those of the Ptch1–/+ tumors, and the expression was enriched in the nucleus." (PMID 38358805, 2024).
tumor (continued). "This latest, is often characterized by activation of Sonic Hedgehog (SHH) signalling, with overexpression of Gli1 and Gli2 that are responsible for the generation of an immunosuppressive tumour microenvironment." (PMID 38886736, 2024). "On the other hand, in medulloblastoma models with constitutively active GLI2, primary cilia ablation accelerated tumour growth." (PMID 39234399, 2024). "Coculture studies showed that the knockdown of Gli2 also abrogated HUVEC recruitment, implicating the role of YAP in promoting tumor angiogenesis by enhancing Gli2/VEGFA expression in RCC cells." (PMID 39123485, 2024). "Overall, the most frequently detected protein was GLI2; it was found in 90% of all tumors, and 66.7% of tumor stromal tissues on average." (PMID 38731849, 2024). "For this purpose, we combined a FISH probe for GLI2, an oncogene carried by ecDNAs in this tumour, and a Xcyte 2 probe allowing us to visualise distinct regions of chromosome 2 with different fluorophores." (PMID 39580568, 2024). "What is especially interesting is the shift of PTCH1 expression, which changes from the healthy stroma to the tumor compartment, and this is matched with the stronger GLI2 staining in the tumor as well." (PMID 38731849, 2024). "The tumor-induced skin expressed mRNA levels of hedgehog genes Gli1, Gli2, and Ptch1 that were 8.1, 4.4, and 3.4 times higher compared to healthy skin (all genes: p < 0.001)." (PMID 38308119, 2024). "GLI2 expression was detected in 87.3% (227/260) of the OSCC tumor lesions and 51.5% (17/33) of the normal tissue lesions." (PMID 38976559, 2024). "Meanwhile, we examined the Hh pathway in tumor xenograft tissues and observed a significant decrease in the levels of the downstream targets of Hh pathway, Gli1 and Gli2." (PMID 38909089, 2024). "The Gli2 activation in tumor exhibiting EMT is found to promote the resistance to PD‐1 inhibitors via upregulating Wnt signaling." (PMID 39092293, 2024). "Gli2 is a TF of the EMT‐related Hedgehog signaling pathway that can impact on the response to anti‐PD‐1 immunotherapy in tumor." (PMID 39092293, 2024). "GLI1 and GLI2 have been found to have overlapping effects on tumor development, while the relationship between GLI3 and the former two is not yet fully understood." (PMID 38498906, 2024). "Regarding the expressions of Gli1 and Gli2, we observed Gli1 and Gli2 expressions in the tumor tissue in the bone marrow in addition to SHH expression." (PMID 37240209, 2023). "In this context, metastatic cells with high expression of GLI2 undergo rapid proliferation through basement tissues, colonize gastric mucosa, and form tumor islands." (PMID 37626893, 2023). "Recently, GLI2 rearrangements were reported to be the hallmark and potential molecular driver event of SST, as they were identified in 81% of these neoplasms." (PMID 38136408, 2023). "In one tumor with PLAGL1 amplification (#A388), we found separate focal high-level amplification of the GLI2 oncogene on chromosome 2q14.2, and in another tumor with PLAGL1 amplification (#A93), we found focal amplification of MYB on chromosome 6q23.3." (PMID 36437415, 2023). "As previous studies report, GLI2 is closely related to Hedgehog in regulating tumor progression, so GLI2 is put into further analysis." (PMID 38159250, 2023). "Collectively, we find down-regulation of tumor-derived GLI2 leads up-regulation of NK-derived IFN-gamma (co-culture)." (PMID 38159250, 2023). "Consistently, in overexpression of Gli2 background, knockdown of spop dramatically upregulated hRpb7 levels in 293T cells and A375, DaoY tumor cells." (PMID 37554435, 2023). "Since more than a quarter of MB patients show activation of the SHH signaling pathway shown by GLI2/1 immunopositivity, activated forms of GLI2 preserve pathway activity and support survival of the tumor cells, indicating GLI2 activity as a key driver for MB." (PMID 37608807, 2023).